MYOD1 (myogenic differentiation 1)
Diseases named in the same sentence as MYOD1 in open-access papers (continued):
Sharing a sentence is not in itself a finding about the gene and the disease.
rhabdomyosarcoma (continued). "Area of rhabdomyosarcoma express desmin and skeletal muscle markers, myogenin and myoD1." (PMID 21663687, 2011). "Immunohistochemically sclerosing rhabdomyosarcoma in adults shows a distinctive immunophenotype in the expression of muscle markers, characterized by positivity for MyoD1, negativity for Myogenin and variable expression for Desmin and Actin muscle specific, as occurred in the elbow tumor." (PMID 20701800, 2010). "The noncartilaginous spindled tumor cells were negative for MyoD1, myogenin, and desmin by immunohistochemical staining (data not shown), thus excluding the possibility that the noncartilaginous component was a variant of rhabdomyosarcoma." (PMID 27248819, 2016). "In immunohistochemical staining, rhabdomyosarcoma (RMS) exhibits positive expression of vimentin, desmin, myogenin, and MyoD1." (PMID 40703554, 2025). "Some alveolar rhabdomyosarcomas can express CD99, but they also express myogenic markers, including myogenin and MyoD1." (PMID 40950824, 2025). "Virtually all examples of TFCP2-rearranged rhabdomyosarcoma are diffusely positive for pancytokeratins, e.g., AE1/AE3, OSCAR, MNF116, and desmin, as well as myogenin and/or MYOD1, with MYOD1 showing higher sensitivity." (PMID 40526340, 2025). "Other examples include rhabdomyosarcoma cells resistant to PAX3 or both PAX3 and MYOD1 KO that had an enhanced dependency on MYC compared to lineage sensitive lines." (PMID 37554444, 2023). "However, the discovery of rhabdomyoblast‐like cells with positive skeletal muscle differentiation markers (Desmin, MyoD1, and Myogenin) in the stromal background, raised the possibility of alternative diagnoses, such as PIS‐DICER1 or rhabdomyosarcoma." (PMID 40040389, 2025). "Thus, we performed IF staining of tumor sections to monitor the accumulation of rhabdomyosarcoma (RMS) markers, including MyoD1 and myogenin." (PMID 38451719, 2024). "The remaining 10/27 MPNSTs variably classified as schwannoma, osteosarcoma, BCOR-altered sarcoma, rhabdomyosarcoma (RMS)-MYOD1 mutant, RMS-like, and embryonal RMS or did not match with any defined entity." (PMID 38178234, 2024). "Focal desmin positivity was seen in two of our cases but the lack of nuclear positivity for MyoD1 and myogenin ruled out a rhabdomyosarcoma." (PMID 37218666, 2024). "The malignant cells being negative for Desmin and MyoD1 negated the possibility of rhabdomyosarcoma, and negativity for LCA helped rule out lymphoma." (PMID 39021466, 2024). "In alveolar rhabdomyosarcoma, the chimeric transcription factor PAX3-FOXO1 interacts with the master transcription factors MYCN, MYOG and BRD4 at target gene super-enhancers, resulting in over-expression of SOX8, MYOD1, MYOG and MYCN, alveolar rhabdomyosarcoma tumorigenesis and dependence on BRD4." (PMID 38135679, 2023). "Spindle cell/sclerosing rhabdomyosarcoma, generally has weak to absent myogenin staining, but strong nuclear MYOD1 staining." (PMID 36173721, 2022). "Rhabdomyosarcoma is more common in children; the tumor cells are commonly positive for myogenic markers (such as MYOD1 and myogenin), but negative for epithelial and neuroendocrine markers." (PMID 34996495, 2022). "Almost all rhabdomyosarcoma samples show positive nuclear staining with antibodies to MyoD1 and/or myogenin, with nonrhabdomyosarcoma pediatric tumors being consistently negative." (PMID 35372059, 2022). "The spindle cells were negative for actin, desmin, Myod1, and myogenin, excluding leiomyosarcoma or rhabdomyosarcoma, and they were also negative for CD21 and CD35, excluding follicular dendritic sarcoma." (PMID 34940081, 2021). "We identified 88 transcription factors, many of which have been described previously as part of the core regulatory transcription factor circuitry in specific cancer types, such as PHOX2B, TWIST1, and ISL1 in neuroblastoma; MYOD1 and MYOG in rhabdomyosarcoma; NR0B1 in Ewing sarcoma." (PMID 34818552, 2021).
rhabdomyosarcoma (continued). "Importantly, SOX4 is highly expressed in embryonal rhabdomyosarcoma compared with normal muscle and knockdown of SOX4 leads to a significant decrease in MYOD1 levels and impaired rhabdomyosarcoma cell survival." (PMID 31941033, 2020). "In this in vitro study, Vincristine and Doxorubicin chemoresistant subpopulations were identified as cells expressing the markers MYOD1 and NOG in two patient-derived soft-tissue tumor models (A-204, a rhabdoid tumor cell line, and RD, an embryonal rhabdomyosarcoma cell line)." (PMID 32300280, 2020). "Rhabdomyosarcoma can be differentiated from IMT based on morphological features (more frequent mitoses with atypical forms and tumor-type necrosis) and the application of an immunohistochemical panel that includes MyoD1 or myogenin." (PMID 25737794, 2015). "A hallmark feature of rhabdomyosarcoma is the expression of muscle marker MyoD1, but despite its high expression in rhabdomyosarcoma, it is non-functional and consequently myogenesis is arrested in this context." (PMID 26204834, 2015). "Alveolar rhabdomyosarcoma was ruled out by negative myogenin and myoD1 and by absence of PAX3/PAX7-FKHR translocations by FISH." (PMID 20598147, 2010). "A final differential diagnosis could be with alveolar rhabdomyosarcoma, which can also display an alveolar pattern, but the diagnosis was ruled out by negativity of Myogenin and MyoD1 staining and no detection of PAX::FOXO1 fusion by NGS." (PMID 38643139, 2024). "Additionally, the lack of MyoD1 and S100 expression eliminates the possibility of rhabdomyosarcoma and melanoma, respectively, as these markers are known to be sensitive to those conditions." (PMID 39162837, 2024). "In addition to SMA and desmin, alveolar and embryonic rhabdomyosarcoma express MyoD1 and myogenin but not CK or neuroendocrine markers." (PMID 34193155, 2021). "However, the lack of desmin, myogenin and MyoD-1 ruled out rhabdomyosarcoma, while LCA negativity ruled out a diagnosis of lymphoma." (PMID 20233457, 2010).
alveolar rhabdomyosarcoma (15 papers, 2010 to 2025). A rapidly growing malignant mesenchymal neoplasm. "For instance, the diagnosis of alveolar rhabdomyosarcoma (ARMS) is typically based on histopathological features, IHC results (most importantly desmin, MyoD1, and myogenin), and molecular results (RT-PCR for PAX3/PAX7–FOXO1 or FISH for PAX3/FOXO1 rearrangement)." (PMID 37621777, 2023).
breast carcinoma (14 papers, 2012 to 2024). "MYOD1 (myogenic differentiation 1) is a transcription factor that inhibits breast cancer differentiation, acting as a tumor suppressor." (PMID 35954483, 2022). "Functional dysregulation and abnormal expression of MyoD1 has been reported in retinoblastoma, head and neck cancer, breast cancer and lung adenocarcinoma." (PMID 34722422, 2021). "As MyoD1 was reported as a negative regulator in breast cancer, these evidences indicated that ID4 could promoted the expression of CBF1 by weakening the inhibition of MyoD1 on CBF1 transcription in breast cancer." (PMID 32328189, 2020). "A direct indication of the accuracy of this part of our experimental approach was the finding that loci previously reported to undergo hypermethylation during breast cancer pathogenesis, such as for examplePAX2, MYOD1 and PITX2, were also detected in our microarray experiments." (PMID 24490656, 2014). "Interestingly, recent studies suggest both a role for FBN1 and MYOD1 in breast cancer." (PMID 32850701, 2020). "However, the mechanism underlying the oncosuppressor role of MYOD1 in breast cancer has not been discovered yet, so investigating its interaction with DDX5 might provide some clues about the molecular pathways involved." (PMID 35954483, 2022). "Since DDX5 acts as an oncogene in breast cancer, the significance of the interaction with DDX5 is unclear, since it was reported that the RNA helicases DDX5 and DDX17 are positive regulators of the transcription activity of MYOD1." (PMID 35954483, 2022). "For example, myogenic differentiation 1 (MYOD1) induces more than 16,000 eRNAs during myogenic differentiation, while estrogen receptor 1 (ESR1) induces thousands of eRNAs to maintain transcriptional circuitry in breast cancer." (PMID 33119754, 2021). "Result showed that ID4 may target the CBF1 pathway by directly binding to its promoter region via combination with MyoD1, therefore CBF1 activated the function of MRP1 to enhance the chemotherapy resistance in breast cancers." (PMID 32328189, 2020). "In our work, we found the Notch1 pathway was positively associated with ID4 expression both in MDA-MB-231 and MCF-7/Adr cells, and ID4 could activate CBF1 by directly binding to the CBF1 promoter region via combined with MyoD1, which was reported to be a negative transcriptor in breast cancer." (PMID 32328189, 2020).
Duchenne muscular dystrophy (14 papers, 2007 to 2025). Duchenne muscular dystrophy (DMD) is a neuromuscular disease characterized by rapidly progressive muscle weakness and wasting due to degeneration of skeletal, smooth and cardiac muscle. "We previously developed MYOD1-transduced UDCs (MYOD1-UDCs) as a model recapitulating the pathogenesis of Duchenne muscular dystrophy (DMD) caused by a lack of dystrophin." (PMID 38282008, 2024).
Obesity (13 papers, 2015 to 2025). Accumulation of substantial excess body fat. "Since obesity is associated with fiber type switching towards fast glycolytic and low oxidative fibers, the observed increase in MyoD1 could potentially be due to a fiber type switch, at least in vivo." (PMID 27532680, 2016). "Exercise by obese dams during pregnancy reversed the maternal obesity induced downregulation of MYOD1 in male offspring." (PMID 25853572, 2015). "Assessing UCP1 and thermogenic gene products (e.g., MyoD1, LHX8, DIO2, PPARGC1A) in tissue materials removed during elective surgery may be used to predict obesity risk and initiate interventions to mitigate further adipose tissue expansion at an early stage." (PMID 38069028, 2023).
embryonal rhabdomyosarcoma (12 papers, 2016 to 2024). A poorly circumscribed morphologic variant of rhabdomyosarcoma. "Patient 47 was initially diagnosed with an embryonal rhabdomyosarcoma but was found in our current analyses to be immunonegative for all of the tested muscle markers including desmin, myogenin, myoglobin, and myoD1." (PMID 37395142, 2023). "The authors found cytoplasmic positivity for desmin and nuclei positivity for myogenin, in embryonal rhabdomyosarcoma, and also in one case positivity for MyoD1 (Peters S., Silva J., Morales L., Beghdad M., Bhandarkar A.,and Shahidatul-Adha M.)." (PMID 36173721, 2022). "Immunohistochemical stains were positive for vimentin, CD99, myogenin, and MyoD1 consistent with a diagnosis of embryonal rhabdomyosarcoma, botryoid subtype." (PMID 29375950, 2017). "Recurrent mutations in the myogenic transcription factor MYOD1 and PIK3CA were initially described in a subset of embryonal rhabdomyosarcomas." (PMID 27562493, 2016). "Myogenic markers (desmin, myogenin, MyoD1) are negative, excluding the differential diagnostic consideration of embryonal rhabdomyosarcoma, which frequently also has myxoid stroma, and shows locally aggressive features on imaging." (PMID 39597961, 2024). "In this study, the myogenic determination factor 1 (MYOD1) and the morphogenetic protein Noggin (NOG) were investigated in an embryonal rhabdomyosarcoma (ERMS) and a rhabdoid tumor (RT) cell line." (PMID 32300280, 2020). "Although embryonal rhabdomyosarcoma most likely arises from myoblasts, both markers of quiescent satellite cells, e.g., PAX3, PAX7, or HEYL, and markers of activated satellite cells, including MYOD1, are frequently expressed." (PMID 31941033, 2020). "The final diagnose was embryonal rhabdomyosarcoma (ERMS) with immunohistochemical staining positivity for myogenin, smooth muscle actin (EMA), desmin and myoD1." (PMID 32736545, 2020). "We ruled out undifferentiated carcinoma, lymphoma, melanoma, and embryonal rhabdomyosarcoma based on negative immunoreactions of PanCK, LCA, HMB45, and MyoD1, respectively." (PMID 39503009, 2024).
gastric cancer (12 papers, 2016 to 2025). A primary or metastatic malignant neoplasm involving the stomach. "On the other hand, abnormal methylation of genes, for example, IGF2, SLC16A2, SOX11, P2RX7, and MYOD1, were identified in H. pylori infection and significantly correlated with gastric cancer and its clinicopathological features." (PMID 41614769, 2025). "In gastric cancer, MYOD1 expression was significantly decreased, and suppresses the migration and invasion of gastric cancer cells by inhibiting FUT4 transcription." (PMID 36118887, 2022). "The MyoD1 was also significantly under expressed in gastric cancer." (PMID 34722422, 2021). "MyoD1 is expressed at significantly lower levels in gastric cancer (GC) tissues and cells, and it induces apoptosis in GC cells." (PMID 31831855, 2020). "We have shown that MyoD1 expression was significantly lower in gastric cancer (GC), and gradually decreased in G1, G2, and G3 GC tissues." (PMID 31831855, 2020).
muscular dystrophy (11 papers, 2011 to 2025). Muscular dystrophy (MD) refers to a group of more than 30 genetic diseases characterized by progressive weakness and degeneration of the skeletal muscles that control movement. "CSRP3 is a plausible EDMD candidate gene because Csrp3 is a mechanosensitive transcription regulator in muscle and cofactor for MyoD1, and also binds LC3 and promotes autophagy as a mechanism of protection against muscular dystrophy." (PMID 37936983, 2023).
muscle atrophy (8 papers, 2013 to 2026). The loss of muscle tissue due to inactivity or disease. "In a muscle atrophy model, the expression of Atrogin-1 and MuRF1 increased, and that of muscle differentiation factors, such as myogenin and MyoD1, decreased." (PMID 35736168, 2022). "To understand how GPRC5D-AS1 and miR-520d-5p affected atrophy cell myogenesis and differentiation, we treated human muscle atrophy model cells with empty plasmid, GPRC5D-AS1-OE plasmid, MYOD1-OE plasmid, associated miRNA control, miR-520d-5p mimic and inhibition." (PMID 38100482, 2023).
melanoma (7 papers, 2010 to 2025). A malignant, usually aggressive tumor composed of atypical, neoplastic melanocytes. "However, only one of the two cases of congenital melanomas exhibited true rhabdomyosarcomatous dedifferentiation, as confirmed by immunohistochemical positivity for myogenin and myoD1." (PMID 40506928, 2025). "The IHC study revealed that LCA, panCK, HNB45, MyoD1, and MALT1 were all negative in the tumoral cells, ruling out lymphoma, malignant melanoma, and undifferentiated carcinoma." (PMID 39503009, 2024). "myogenic differentiation 1 (MYOD1), desmin, wilms tumor 1 (WT1), CD57,transducin-like enhancer of split 1 (TLE1), melanoma/prostate markers, chromogranin A, andinhibin were negative." (PMID 34106022, 2021).
neuroblastoma (7 papers, 2014 to 2025). Neuroblastoma (NB) is the most common solid, extracranial childhood tumor.
sarcoma (7 papers, 2015 to 2025). A usually aggressive malignant neoplasm of the soft tissue or bone. "Immunohistochemistry for BCOR and MYOD1 were positive in the two cases classified as BCOR-rearranged sarcoma and MYOD1-mutant RMS, respectively (#11 and #12), thus corroborating the diagnoses suggested by DNAm profiling." (PMID 38178234, 2024). "Pathological analysis revealed high-grade sarcomas with myogenic differentiation based on the expression of muscle-specific markers, such as Myod1 and Myog." (PMID 25992772, 2015). "The absence of lineage-specific markers, including EMA, CD34, CD31, myogenic markers (MyoD1, myogenin), melanocytic markers (HMB-45), and lymphoid markers (CD45), helped exclude alternative diagnoses such as sarcomas and hematologic malignancies." (PMID 41552210, 2025). "The differential diagnosis for such a localization is mainly with EXING sarcoma, so it is important to have pathohistological examination for MyoD1(which confirms RMS), CD 99 and EWSR1 gene evaluation (which could confirm EWING sarcoma)." (PMID 39767925, 2024).
spindle cell rhabdomyosarcoma (7 papers, 2017 to 2022). An uncommon variant of rhabdomyosarcoma characterized by the presence of whorls of spindle cells forming a storiform pattern. "There are a number of other bone and soft tissue tumors which harbor recurrent point mutations including a MYOD1 p.L122R mutation in a large percentage of spindle cell rhabdomyosarcoma 16, 17, an exceptionally rare, and aggressive high‐grade tumor." (PMID 28834325, 2017). "Presurgery mutant MYOD1 p.L122R ctDNA was detected in 2/3 patients with a spindle cell rhabdomyosarcoma, all of which harbored the characteristic recurrent mutation in their tumors." (PMID 28834325, 2017). "This feature is characteristic of spindle cell rhabdomyosarcomas (RMS), which show recurrent MYOD1 p.L122R mutation." (PMID 33468253, 2021). "And strongly positive for desmin and MyoD1 in the spindle cell rhabdomyosarcoma case." (PMID 36173721, 2022). "Immunohistochemical analysis showed negative staining with Cytokeratin, S100, CD34, Stat6, h-Caldesmon and EMA while the tumour cells were positive for desmin, myogenin, smooth muscle actin, CD-99 and MyoD1 thus confirming the diagnosis of spindle cell rhabdomyosarcoma." (PMID 34104191, 2021). "Moreover, the RNA-seq results refined the consensus diagnosis in 5 (11%) additional patients, including SRF-NCOA1 in spindle cell rhabdomyosarcoma, MYOD1 p.L122R in sclerosing rhabdomyosarcoma, TPM4-ALK in inflammatory myofibroblastic tumor, and BCOR-CCNB3 in clear cell sarcoma of the kidney." (PMID 34131151, 2021). "Positivity for epithelial antibody markers and negative staining for skeletal muscle-specific markers, namely desmin, myogenin and MyoD1, ruled out a spindle cell rhabdomyosarcoma." (PMID 34514569, 2022).
cervical cancer (6 papers, 2012 to 2025). A primary or metastatic malignant neoplasm involving the cervix. "The hypermethylation of MYOD1 has been reported to be a prognostic biomarker for both colorectal and cervical cancers." (PMID 31242667, 2019). "In conclusion, the present studies clearly showed that MEG3, MYOD1, CALCA, hTERT, and RASSF1A methylation in plasma can serve as diagnostic and prognostic biomarkers for cervical cancer patients, providing useful information for clinical management." (PMID 29850477, 2018). "BRCA2, DAB2IP, and the DNA-PKcs inhibitor NU7441 are prostate cancer-related markers, while the methylation of ESR1 and MYOD1 and expression of SEPT9 correlate with radiotherapy response in cervical cancer." (PMID 40277781, 2025). "In general, mRNA expression levels are lower in cervical cancer cells lines than in HaCaT cells, except for SOX17 and MYOD1 in SiHa cells, MGMT in C-33A cells and AJAP1, SOX17 and MYOD1 in HeLa cells." (PMID 34991696, 2022). "Promoter hypermethylation of some other genes like MYOD1, CALCA, hTERT, and RASSF1A can also be detected in serum samples of cervical cancer patients and are related to lymph node metastasis and FIGO stage." (PMID 29850477, 2018).
soft tissue sarcoma (6 papers, 2014 to 2025). A malignant neoplasm arising from muscle tissue, adipose tissue, blood vessels, fibrous tissue, or other supportive tissues excluding the bones. "This is in agreement with our survival analysis on soft-tissue sarcomas demonstrating that upregulated expression of ALDH6A1 but not ALDH1A1 or ALDH3A1 significantly correlates with poor survival when combined with other genes identified in our model, i.e., CDH15, MYOD1, SOX4, ARMCX1, and RYK." (PMID 31941033, 2020).